PBX1 (PBX homeobox 1)
Diseases named in the same sentence as PBX1 in open-access papers (continued):
Sharing a sentence is not in itself a finding about the gene and the disease.
focal segmental glomerulosclerosis (1 paper, 2025). A renal disorder characterized by sclerotic lesions in the glomeruli. "Here, we report the case of a 28-year-old man who was initially diagnosed with focal segmental glomerulosclerosis (FSGS) and acute tubular necrosis of unknown etiology, and was later found to carry a de novo PBX1 nonsense variant." (PMID 41255624, 2025).
intestinal cancer (1 paper, 2023). "Collectively, PBX1 overexpression reduced mitotic progression and suppressed the proliferation of intestinal cancer cells." (PMID 36739270, 2023).
intrahepatic cholangiocarcinoma (1 paper, 2024). A carcinoma that arises from the intrahepatic bile duct epithelium in any site of the intrahepatic biliary tree. "Data integration reveals PBX1 as a central gene for intrahepatic cholangiocarcinoma." (PMID 38877653, 2024).
lobular carcinoma (1 paper, 2015). "For example, PBX1 ranks in the top 50 most overexpressed genes in ductal and lobular carcinoma compared to normal tissue in TCGA cohort." (PMID 26215677, 2015).
metastatic disease (1 paper, 2015). "We then measured PBX1 amplification using a qPCR assay in cfDNA from 37 patients with ERα-positive primary disease and 50 patients with ERα-positive metastatic disease treated with endocrine therapy." (PMID 26215677, 2015).
myelodysplastic syndrome (1 paper, 2025). A clonal hematopoietic disorder characterized by dysplasia and ineffective hematopoiesis in one or more of the hematopoietic cell lines. "Notwithstanding the previously cited data indicating PBX1’s involvement in MPNs, no studies have delineated its role in myelodysplastic syndromes (MDSs)." (PMID 41226583, 2025).
nephrolithiasis (1 paper, 2019). The presence of a calculus in the pelvis of the kidney; this is most often composed of mineral salts and proteins. "We postulate that the presence of this SNP alters the expression of PBX1, thus affecting the renal absorption of cystine and other amino acids, predisposing to nephrolithiasis." (PMID 30450686, 2019). "PBX1 is a member of a transcription factor family, and there are no studies associating this gene with nephrolithiasis, although it has been associated with kidney development." (PMID 30450686, 2019).
oral squamous cell carcinoma (1 paper, 2024). "The downregulation of PBX1 increases the radiosensitivity of oral squamous cell carcinoma cells and xenograft tumors through the PBX1/STAT3 pathway." (PMID 39129784, 2024).
ovarian serous carcinoma (1 paper, 2012). "By analyzing TCGA gene expression microarray datasets from ovarian serous carcinomas, we found co-upregulation of PBX1 and a significant number of its direct target genes." (PMID 22567123, 2012).
pancreatitis (1 paper, 2011). Inflammation of the pancreas. "Expression of stellate cell markers CELSR3, PBX1 and GFAP was observed in BMD cancer-associated PaSCs, however cancer-associated, but not pancreatitis-associated BMD PaSCs, expressed the cancer PaSC specific marker CELSR3." (PMID 22022519, 2011).
Polycythemia Vera (1 paper, 2025). "In certain MPN patients with the JAK2V617F mutation, an alteration in the copy number of PBX1 was seen, accompanied by elevated expression levels in CD34+ cells in Polycythemia Vera (PV) patients." (PMID 41226583, 2025).
renal carcinoma (1 paper, 2023). A carcinoma arising from the epithelium of the renal parenchyma or the renal pelvis. "Furthermore, the expression of PBX1 was dynamically upregulated in four renal carcinoma cell lines (OS-RC-2, KAKi-2, 786-O, and 769-P) and the HK-2 proximal renal tubule cell line." (PMID 37006624, 2023).
renal cell carcinoma (1 paper, 2021). "Additionally, PBX1 haploinsufficiency has been linked to congenital anomalies of the kidney and urinary tract, reported to be involved in the proliferation of cells in renal cell carcinoma and has been recognised as a candidate gene for T2DM." (PMID 33933144, 2021).
renal malformation (1 paper, 2022). "With molecular cytogenetic techniques especially CMA, some of patients harboring microdeletions with precise breakpoints were reported, which offered the opportunity to identify PBX1 as a promising candidate gene associated with renal malformation." (PMID 36544198, 2022).
Splenomegaly (1 paper, 2025). Abnormal increased size of the spleen. "Similarly, splenomegaly was most common in SIL::TAL1 patients (100%), followed by E2A::PBX1 (75%), BCR::ABL (60%), MLL::AF4 (33.3%), TEL::AML1 (30%), negative (29.7%) and unknown (25.6%)." (PMID 41234729, 2025).
thymoma (1 paper, 2020). A neoplasm arising from the epithelial cells of the thymus. "This analysis revealed that Meis1-3, Pbx1-3, and Hoxa9 genes are highly upregulated in thymoma when compared to healthy adult tissues." (PMID 33402862, 2020).
cancer (60 papers, 2009 to 2025). A tumor composed of atypical neoplastic, often pleomorphic cells that invade other tissues. "Like the HOX family, PBX1 has a strong correlation with organogenesis, differentiation, and development, and it is also a key character of the hallmarks of cancer, its up-regulation of expression is linked to carcinogenesis and a worse prognosis." (PMID 39980564, 2025). "The dysregulation of PBX1 has been linked to the initiation and advancement of multiple cancer types via the promotion of tumor cell proliferation through interactions with specific proteins or alterations in the transcription of target genes." (PMID 41226583, 2025). "The results from the survival curves indicate that high PBX1 expression is associated with survival rates in these cancer patients." (PMID 39129784, 2024). "On the other hand, PBX1 aberrant expression is linked to cancer in several of the tissues in which it plays a role during development." (PMID 38404687, 2024). "First described in rare forms of acute leukemia through the formation of a fusion transcript with E2A, PBX1 proved to be a protein implicated in various forms of cancer but also as a key factor of embryonic development." (PMID 36833200, 2023). "The aberrant PBX1 expression is associated with poor prognoses, tumorigeneses, resistance to cancer therapy, and poor response to induction therapy." (PMID 37006624, 2023). "While studying the underlying mechanism of Pax5 expression in NE-like cancer, we observed the involvement of Pbx1 in Pax5 transcription." (PMID 38168280, 2023). "Deregulation of Hox protein cofactors MEIS2, MEIS1 and Pbx1 are associated with cancer oncogenesis and tumor progression." (PMID 24391925, 2013). "Both PBX1 and E2A-PBX1 have been implicated in cancer, where they may drive oncogenic processes through aberrant gene regulation and interactions with oncogenic partners." (PMID 39129784, 2024). "Thus, development of small molecule inhibitors targeting PBX1 transcriptional signaling could serve as a novel therapeutic strategy for PBX1-associated cancers." (PMID 39129784, 2024). "Therefore, developing small molecule inhibitors targeting PBX1 transcriptional signaling could be a novel therapeutic strategy for PBX1-associated cancers." (PMID 39129784, 2024). "PBX1 acts as a major regulator in cancer by orchestrating many oncogenic signaling pathways that facilitate tumor formation and progression." (PMID 41226583, 2025). "PBX1 contributes to the development of cancer involving the tissues and cell lineages that it normally regulates during development." (PMID 38404687, 2024). "We believe that as research progresses and understanding of the oncogenic mechanisms of PBX1 and E2A-PBX1 deepens, the development of specific drugs against their targets would be key to treating their related cancers." (PMID 39129784, 2024). "We here discuss differences and analogies of PBX1 roles during embryonic development and in cancer, focusing mainly on the most recent discoveries." (PMID 38404687, 2024). "Other cancers in which PBX1 exert a tumor suppressor role are liver cancer, glioma and oral carcinoma." (PMID 38404687, 2024). "Cancer cells overexpressing PBX1 exhibit enhanced growth, invasion, epithelial-mesenchymal transition (EMT), and cisplatin resistance, whereas PBX1 silencing exhibits the opposite effect." (PMID 39129784, 2024). "Pre-B cell leukemia homeobox 1 (PBX1) is a transcription factor upregulated in various malignant tumors." (PMID 39090090, 2024). "Summary of the role of PBX1 during development, mostly discovered through the analysis of mutant mice or embryos, and role in cancer or other diseases affecting the same tissues whose development depend on PBX1." (PMID 38404687, 2024).
cancer (continued). "In tumor cells, ectopic expression of PBX1 promotes cancer stem cell-like phenotypes, including platinum chemoresistance." (PMID 37175439, 2023). "Our results indicate that Pbx1 is selectively overexpressed in NE-like cancers, which was further validated in patient’s gene expression data." (PMID 38168280, 2023). "PBX1 is a canonical transcription factor that controls the progression of various cancers in eukaryotic cells." (PMID 36739270, 2023). "First, the subinteractomes of these ORF proteins contain proteins associated with ‘cancer hallmark’ and oncoproteins (e.g., the case of C5orf24 and its protein partners XPO1, PBX1, MYC, CIC, GOPC, CREB1 and STK11)." (PMID 37373333, 2023). "PBX1 has been reported to promote tumorigenesis in various cancers, but its role in NSCLC is not well understood." (PMID 37324936, 2023). "PBX1 has been reported to be a transcription factor in many types of cancers, influencing tumor biological behavior and malignant progression." (PMID 36739270, 2023). "For instance, our previous work found that the level of PBX1 mRNA was 3.298‐fold elevated in BC tissue compared within adjacent normal tissues in a clinical cohort of 593 specimens from The Cancer Genome Atlas database." (PMID 35068042, 2022). "PBX1 was also found to promote the resistance of PCa cells to common anti‐cancer drugs such as doxorubicin and cisplatin." (PMID 35068042, 2022). "It is interesting to note that miR-193a provides a possible link between cancer stemness and immunoevasion, as PBX1 (which is another predicted target of miR-193a), as well as the transcriptional activator for the immunosuppressive cytokine IL-10." (PMID 35216394, 2022). "The downregulation of EFNB2 and PBX1 in the cancer cells (A2780, IGROV-1 and HEC1A) with sfTSLP overexpression was confirmed by qRT-PCR." (PMID 33652749, 2021). "Targeting of PBX1-HOX interactions by peptide-competition has been applied in various types of cancer." (PMID 33539429, 2021). "Among these transcription factors, HOXA9 and PBX1 have been reported to function as drivers in drug resistance of multiple cancer types." (PMID 32703314, 2020). "Several small molecules and synthetic peptides can mimic the hexapeptide motif to competitively bind with the hexapeptide binding pocket of PBX1 and suppress tumorigenesis in various cancers." (PMID 28514754, 2017). "PBX1 was predominantly present in the nuclei, and partially expressed in the cytoplasm of cancer cells." (PMID 28514754, 2017). "PBX1, itself, is a product of a proto-oncogene, which suggests a role in tumorigenesis, metastasis, and chemoresistance in various cancers." (PMID 28514754, 2017). "PBX1 is pre-bound to shared PBX1-ERα binding sites proximal to genes involved in cancer cell proliferation prior to estrogen application and its binding to these sites remains following estrogen treatment." (PMID 28261581, 2017). "Potentially, this would allow for monitoring PBX1 levels by measuring its amplification in DNA derived from cancer cells using non-invasive methods." (PMID 26215677, 2015). "Retrospective stratification of luminal patients using PBX1 protein levels in primary cancer further demonstrates that elevated PBX1 protein levels correlate with earlier metastatic progression." (PMID 26215677, 2015). "Although MEOX1 is well-established as one of the key transcriptional regulators during embryonic development, our results demonstrate that MEOX1 is also involved in cancer development through participating in the PBX1 transcriptional network." (PMID 22567123, 2012). "Further experiments should be performed to determine if other cofactors serve as co-regulatory factors with PBX1 in cancer cells." (PMID 22567123, 2012). "Based on this rationale, we performed a “rescue” assay by ectopically expressing MEOX1 in cancer cells with PBX1 knockdown." (PMID 22567123, 2012).
cancer (continued). "In light of the potential role of PBX1 in various cancer types, identifying the PBX1 transcription target genes in cancer cells is critical to elucidating its oncogenic mechanisms." (PMID 22567123, 2012). "Seven representative candidates, based on their known functions in cancer biology, were selected from the 195 candidate PBX1 targets for validation using qPCR." (PMID 22567123, 2012). "The results as reported here represent a first step toward understanding the complex regulatory network of PBX1 in carcinomas." (PMID 22567123, 2012). "The fact that MEOX1 is co-upregulated with PBX1 in a subset of ovarian carcinomas suggests that a PBX1-MEOX1 molecular axis is involved in the transcriptional regulation of these carcinomas." (PMID 22567123, 2012). "Recent studies indicate that PBX1 is integral to the progression of various cancers." (PMID 41226583, 2025). "PBX1 could serve as a therapeutic target due to its interaction with various genes and pathways that facilitate cancer development." (PMID 41226583, 2025). "Understanding PBX1’s function and role in oncogenesis could aid researchers in identifying biomarkers that could enhance cancer prediction and diagnosis, as well as new therapeutic targets and strategies." (PMID 41226583, 2025). "In cancer, PBX1 was first identified as a fusion gene partner in pre‐B‐cell leukemia." (PMID 38877653, 2024). "Here, we summarized the expression levels of PBX1 in various cancer types (data derived from TCGA), and plotted survival curves for patients with high PBX1 expression that exhibited statistically significant differences (Gene expression profiles were obtained from TCGA." (PMID 39129784, 2024). "The development of specific drugs against their targets may be a good therapeutic strategy for PBX1-related cancers." (PMID 39129784, 2024). "PBX1 is an important player in development, adult tissue homeostasis and cancer." (PMID 38404687, 2024). "In some cancers, decreased expression of PBX1 favors malignancy." (PMID 38404687, 2024). "In recent decades, data have shown that PBX1 contributes to the carcinogenesis of several cancers." (PMID 38877653, 2024). "The role of PBX1 in tumor progression varies across different cancer types." (PMID 39129784, 2024). "Similarly, we observed an association of HOXA9 with PBX1, PBX2, PBX3, and MEIS1 in all 10 cancer types except for STAD." (PMID 38904676, 2024). "Mutated PBX1 proteins also have dominant-negative effects and are able to abolish proliferation in a cancer cell line." (PMID 36833200, 2023). "The decrease in STAT3Tyr705 phosphorylation after PBX1 knockout in ccRCC cells may also influence cancer cell growth and play an important role in renal tumor development." (PMID 37006624, 2023). "In summary, in most types of cancer, PBX1, 2 and 3 act as an oncoproteins to contribute to cancer progression by promoting drug resistance, CSC‐like phenotypes, proliferation, cell cycle, EMT, invasion and metastasis as well as angiogenesis, and by inhibiting apoptosis." (PMID 35068042, 2022). "Eight genes satisfied both criteria, including BRCA1/2 and a known cancer gene PBX1." (PMID 35625955, 2022). "Activation of Notch signaling pathways might upregulate the downstream targets of Notch, such as PBX1, to drive the stemness and carcinogenesis of cancer." (PMID 32169072, 2020). "In conclusion, multiple lines of evidence, obtained from in vivo and in vitro studies and made in the context of embryonic development, adult stem cell differentiation and cancer, suggest that PBX1 may act as pioneer factor." (PMID 28261581, 2017). "Furthermore FOXA1 and GATA3 are frequently downregulated in basal tumour but rarely over-expressed or amplified in luminal cancer while PBX1 is among the top upregulated genes and is frequently amplified in luminal cancers." (PMID 26215677, 2015). "Emerging results have indicated a role of PBX1 in human cancer." (PMID 22567123, 2012).